ALKBH5 (alkB homolog 5, RNA demethylase)
Diseases named in the same sentence as ALKBH5 in open-access papers (continued):
Sharing a sentence is not in itself a finding about the gene and the disease.
liver fibrosis (10 papers, 2021 to 2026). "Second, deletion of ALKBH5 was reported to be associated with worsening clinical liver fibrosis in collected clinical liver fibrosis samples." (PMID 37056286, 2023). "The occurrence of liver fibrosis could be caused by multiple factors, and ALKBH5 played significant roles in this process." (PMID 39220683, 2024). "ALKBH5 is down‐regulated in liver tissues of a CCL4‐induced mouse liver fibrosis model and in TGF‐β‐stimulated activated HSC in vitro, whereas high expression of ALKBH5 ameliorates liver fibrosis and inhibits HSC activation." (PMID 36792369, 2023). "Therefore, this review summarizes the research progress of ALKBH5 in various fibrosis-related cells and diseases such as pulmonary fibrosis, liver fibrosis, cardiac fibrosis, and renal fibrosis." (PMID 39220683, 2024). "In a mouse model of CCl4-induced liver fibrosis, global m6A levels were increased in fibrotic livers compared to normal mouse livers and this m6A increase was inversely correlated to a significant decline in ALKBH5 expression." (PMID 37628704, 2023). "In liver fibrosis, ALKBH5 inhibits the mitochondrial fission, proliferation and migration of hematopoietic stem cells in a YTH domain family protein 1 (YTHDF1)‐dependent manner by reducing the m6A modification of Drp1, which provides a valuable strategy for liver fibrosis diagnosis and therapy." (PMID 37537731, 2023). "ALKBH5 regulated liver fibrosis by affecting the stability of PTCH1 mRNA in an m6A-mediated manner." (PMID 37227534, 2023). "When PTCH1 is hypermethylated, PTCH1 expression is downregulated and HSCs are activated, while ALKBH5 upregulates PTCH1 expression and improves or alleviates liver fibrosis." (PMID 37056286, 2023). "ALKBH5 inhibited mitochondrial fission and HSC proliferation and migration by reducing Drp1 methylation in an m6A-YTHDF1-dependent manner, ultimately ameliorating liver fibrosis." (PMID 39220683, 2024). "Furthermore, ALKBH5 reduced Drp1 methylation in an m6A-YTHDF1-dependent manner, inhibiting HSC proliferation, and migration, thereby ameliorating liver fibrosis." (PMID 39220683, 2024). "Conversely, overexpression of ALKBH5 inhibited HSC activation and suppressed liver fibrosis." (PMID 37628704, 2023). "In the liver fibrosis mice, the m6A methylation abundance was significantly decreased as well as the expressions of WTAP, ALKBH5 and YTHDF1, and the decreased expression of WTAP has been shown to induce the development of liver fibrosis and promote hepatic stellate cell (HSC) activation." (PMID 37227534, 2023). "In vitro and in vivo models, including HSCs and clinical cases or CCl4-induced mice liver fibrosis, ALKBH5 triggered PTCH1 activation in an m6A-dependent manner, leading to hedgehog signaling inactivation, which inhibited the transformation of HSCs into myofibroblasts and ameliorated liver fibrosis." (PMID 39220683, 2024).
renal cell carcinoma (10 papers, 2020 to 2025). "The fat mass and obesity-associated protein (FTO) and alkB homolog 5 (ALKBH5), two RNA demethylases, have opposing effects on renal cell carcinoma (RCC)." (PMID 40361322, 2025). "This study was the first to show that MANF promoted tumor growth in renal cell carcinoma by reducing UPR through ALKBH5 epigenetic regulation." (PMID 40603319, 2025). "The fat mass and obesity-associated protein (FTO) and alkB homolog 5 RNA demethylase (ALKBH5) are RNA-demethylating proteins that have contrasting effects in renal cell carcinoma (RCC) among different populations." (PMID 40361322, 2025). "AURKB expression is up-regulated in renal cell carcinoma and positively correlated with the expression of ALKBH5." (PMID 38396874, 2024). "Taken together, our data indicated that elevated levels of the m6A demethylase ALKBH5 in renal cell carcinoma may lead to increased expression of downstream MANF, activating tumor cell UPR, and resulting in cells proliferation and invasion." (PMID 40603319, 2025). "Similarly, we found that ALKBH5 function was closely related to the cell cycle and renal cell carcinoma." (PMID 35982895, 2022). "However, in our ongoing research, we found that the m6A methyltransferase WTAP and the m6A demethylase ALKBH5 act as oncogenes in renal cell carcinoma." (PMID 32808488, 2020). "Interestingly, the down‐regulated expression of ALKBH5 and FTO was found to be related to poor overall survival and cancer‐specific survival in renal cell carcinoma, which implied that ALKBH5 and FTO could serve as potential prognostic biomarkers." (PMID 32808488, 2020). "The findings of this study indicated that the m6A eraser ALKBH5 upregulated MANF in a YTHDF2-dependent fashion, thereby conferring protection against ER stress-induced cell death in renal cell carcinoma." (PMID 40603319, 2025). "ALKBH5 stabilizes AURKB mRNA in an m6A-dependent manner, thereby promoting the development of renal cell carcinoma." (PMID 38396874, 2024).
clear cell renal cell carcinoma (9 papers, 2020 to 2025). "Our study delved into a novel mechanism through which ALKBH5 facilitated the transcription of MANF in clear cell renal cell carcinoma via a YTHDF2-dependent regulatory manner." (PMID 40603319, 2025). "Knockdown of ALKBH5 can also restrain the malignant potential of clear cell renal cell carcinoma cells by repressing EMT." (PMID 39287046, 2024). "As for other cancers, ALKBH5 was significantly downregulated in clear cell renal cell carcinoma (ccRCC) compared to normal tissue." (PMID 32742194, 2020). "In clear cell renal cell carcinoma (ccRCC), ALKBH5 expression was positively correlated with the length of overall survival, indicating that ALKBH5 could be used as a prognostic biomarker." (PMID 37007161, 2023).
prostate carcinoma (9 papers, 2015 to 2025). A carcinoma that arises from epithelial cells of the prostate gland. "It was found that the expression of METTL14, IGF2BP3, HNRNPA2B1, and CNV of ALKBH5 were linked to the recurrence-free survival of prostate cancer." (PMID 34899855, 2021). "The result has shown that gene-level deletion of YTHDF3 (HR 0.42, 95% CI 0.19-0.95), FTO (HR 0.57 95% CI 0.35-0.9) and amplification of ALKBH5 (HR 2.48 95% CI 1.39-2.42) were risk factors of prostate cancer biochemical recurrence." (PMID 32710725, 2020). "We presented IGF2BP3, HNRNPA2B1 and METTL14 were significantly related to RFS of prostate cancer based on mRNA expression information, while in the CNV-based regression model, YTHDF2, FTO, and ALKBH5 were notably associated with prognosis of prostate cancer." (PMID 32710725, 2020). "Meanwhile, two important m6A “erasers”, FTO and ALKBH5 were significantly down-regulated in prostate cancer patients." (PMID 32710725, 2020). "Seven m6A methylation-related genes (ALKBH5, FMR1, IGFBP3, RBM15B, YTHDF1, YTHDF2, and ZC3H13) were identified as cross-talk genes between prostate cancer and PD." (PMID 36133437, 2022). "Specifically, copy number loss of HNRNPC, METTL3, and FTO were significantly correlated with poor survival of prostate cancer, while patients with copy number gain of RBM15 and ALKBH5 had worse RFS." (PMID 32710725, 2020). "The demethylase ALKBH5 with m6A binding proteins YTHDF1/2/3, concurrently, played a suppression role in the regulation of NSCLC tumor growth and metastasis, while FTO inhibits tumorigenesis in prostate cancer." (PMID 41157107, 2025). "We found that the CNVs patterns of HNRNPC, METTL3, RBM15, ALKBH5 and FTO (one reader, two writers, and two erasers) were notably associated with RFS of prostate cancer." (PMID 32710725, 2020). "However, the expression patterns of the other four genes (ALKBH5, RBM15B, YTHDF1, and YTHDF2) in prostate cancer and periodontitis were not consistent." (PMID 36133437, 2022).
pulmonary fibrosis (9 papers, 2022 to 2024). Chronic progressive interstitial lung disorder characterized by the replacement of the lung tissue by connective tissue, leading to progressive dyspnea, respiratory failure, or right heart failure. "Similarly, another study on PM2.5 exposure‐induced pulmonary fibrosis reported a reduction in ALKBH5 levels, revealing that ALKBH5 deficiency exacerbated the fibrotic condition." (PMID 39233335, 2024). "In a mouse model of silica-induced pulmonary fibrosis, ALKBH5 promoted lung fibroblast activation and silica-induced pulmonary fibrosis via the miR-320a-3p/FOXM1 axis or targeting FOXM1 directly." (PMID 39220683, 2024). "Our previous study revealed that AlkB homolog 5 (ALKBH5) is involved in regulating silica-induced pulmonary fibrosis." (PMID 38105235, 2023). "To further interrogate our results, we examined ALKBH5 expression during the activation of fibroblasts, the principal cells responsible for pulmonary fibrosis." (PMID 35279083, 2022). "We characterized the expression pattern of the critical demethylase ALKBH5 during silica-induced pulmonary fibrosis." (PMID 35279083, 2022). "Our work further confirmed that FOXM1 is the direct and functional target of miR-3p, and finally revealed the ALKBH5/miR-320q-3p/FOXM1 axis in lung fibroblasts activation during silica-induced lung fibrosis." (PMID 35279083, 2022). "Here, we sought to investigate the function of ALKBH5 in pulmonary fibrosis triggered by silica inhalation." (PMID 35279083, 2022). "Our study is not free of limitations; for example, although we verified the upregulation of ALKBH5 in silica-induced mouse pulmonary fibrosis tissues, the intervention effect remains unclarified in vivo and must be addressed in further investigations." (PMID 35279083, 2022). "And ALKBH5 promoted silica-induced lung fibrosis through miR-320a-3p/forkhead box protein M1 (FOXM1) pathway or targeting FOXM1 directly." (PMID 36494831, 2022). "ALKBH5 promotes silica-induced pulmonary fibrosis through miR-320a-3p/forkhead box protein M1 (FOXM1) axis or directly targeting FOXM1." (PMID 36553648, 2022). "Our findings suggest that ALKBH5 promotes silica-induced lung fibrosis via the miR-320a-3p/FOXM1 axis or targeting FOXM1 directly." (PMID 35279083, 2022). "The present findings indicate that m6A modification regulated by ALKBH5 is a novel target for potential lung fibrosis therapy." (PMID 35279083, 2022). "AlkB homolog 5 (ALKBH5), a well-known m6A demethylase, is upregulated in the silica-induced mouse pulmonary fibrosis model." (PMID 35279083, 2022). "The present findings suggest that ALKBH5 promotes silica-induced lung fibrosis via the miR-320a-3p/FOXM1 axis or by targeting FOXM1 directly in an m6A-dependent manner." (PMID 35279083, 2022). "ALKBH5 had been found to regulate pulmonary fibrosis in various animal models." (PMID 39220683, 2024). "Our data provide a proof of concept that targeting ALKBH5 may be efficacious in treating lung fibrosis." (PMID 35279083, 2022). "To validate this hypothesize, we demonstrate herein that ALKBH5 is upregulated and plays a profibrotic role in silica-induced lung fibrosis and TGF-β1-stimulated fibroblast activation." (PMID 35279083, 2022). "In our earlier work, miR-320a-3p was downregulated in silica-induced lung fibrosis, leading us to hypothesize that ALKBH5 may modulate miR-320a-3p processing in an m6A-dependent manner." (PMID 35279083, 2022). "However, some studies had also found that downregulating ALKBH5 might promote the development of pulmonary fibrosis." (PMID 39220683, 2024). "Therefore, the impact of ALKBH5 on pulmonary fibrosis still requires further elucidation." (PMID 39220683, 2024). "ALKBH5 was significantly upregulated and increased in a dose-dependent manner when treated with TGF-β1 (0, 1, 2, and 5 ng/ml) for 48 h, suggesting that ALKBH5 may be associated with the silica-induced pulmonary fibrosis process." (PMID 35279083, 2022).
pulmonary fibrosis (continued). "Thus, we assessed whether ALKBH5 was required for pri-miR-320a-3p processing in fibroblast activation during silica-induced pulmonary fibrosis." (PMID 35279083, 2022). "Interestingly, we find that ALKBH5 can also target FOXM1 directly in pulmonary fibrosis." (PMID 35279083, 2022). "Approaches aimed at ALKBH5 may be efficacious in treating lung fibrosis." (PMID 35279083, 2022). "Research had found that 1-NP promoted ALKBH5 degradation, regulating lung epithelial cells senescence through FBXW7 m6A modification, ultimately leading to 1-NP-induced pulmonary fibrosis (Li SR." (PMID 39220683, 2024). "Knockdown of ALKBH5 significantly upregulated the YAP1 signaling pathway in NIH3T3 cells and lung tissue, promoting extracellular matrix deposition in PM2.5 exposure-induced pulmonary fibrosis of mice." (PMID 39220683, 2024). "Studie had discovered that ALKBH5 could regulate fibroblast-to-myofibroblast differentiation via the miR-320a-3p/FOXM1 axis or targeting FOXM1 directly, promoting silica-induced pulmonary fibrosis." (PMID 39220683, 2024). "Moreover, 1‐nitropyrene promoted ALKBH5 SUMOylation and subsequent proteasomal degradation; consequently, increasing the m6A modification of FBXW7 contributed to pulmonary fibrosis by regulating alveolar cell senescence." (PMID 39233335, 2024). "Despite the many cancer and noncaner studies about ALKBH5, the importance of ALKBH5 expression in silica-induced pulmonary fibrosis remains unclear." (PMID 35279083, 2022). "However, in silica-induced pulmonary fibrosis, whether DDX3 is required for ALKBH5 to regulate the methylation status of miR-320a-3p and FOXM1 needs to be further investigated." (PMID 35279083, 2022).
thyroid cancer (9 papers, 2021 to 2025). "ALKBH5, another RNA m6A demethylase, also functions as a tumor suppressor in thyroid cancer cells by decreasing the expression of GPX4 and SLC7A11 to induce ferroptosis." (PMID 40819127, 2025). "Several molecular pathways, such as the METTL3/c-Rel/IL-8 axis, ZC3H13/hsa_circ_0101050 axis, and ALKBH5/circNRIP1/PKM2 axis, are closely associated with thyroid cancer progression and poor prognosis." (PMID 40819127, 2025). "Overall, the m6A demethylase ALKBH5 induces ferroptosis to inhibit thyroid cancer progression in an m6A-demethylation-dependent manner." (PMID 40819127, 2025). "However, recent research has demonstrated that ALKBH5, an RNA demethylase homologous to AlkB, can impede the progression of thyroid cancer by inducing ferroptosis in thyroid cancer cells via the TIAM1-Nrf2/Heme Oxygenase 1 (HO-1) axis, as evidenced by both in vitro and in vivo studies." (PMID 39917169, 2025). "ALKBH5 modulates TIAM1 expression via m6A modification, thereby promoting ferroptosis in thyroid cancer cells." (PMID 39917169, 2025). "The results demonstrated a reduction in ALKBH5 expression and an elevation in T-cell lymphoma invasion and metastasis 1 (TIAM1) expression in thyroid cancer." (PMID 39917169, 2025). "We showed that METTL14, FTO, and ALKBH5 were down-regulated in most cancers, whereas YTHDF1 and IGF2BP3 were up-regulated in 12 cancer types except for thyroid carcinoma (THCA)." (PMID 33718187, 2021). "In addition, ALKBH5 overexpression downregulates TIAM1 expression by eliminating the m6A modification of TIAM1 mRNA, suppresses thyroid cancer cell proliferation and promotes ferroptosis by regulating the Nrf2/HO-1 pathway." (PMID 40819127, 2025). "Additionally, ALKBH5 induces ferroptosis through the m6A-TIAM1-Nrf2/HO-1 axis, thereby inhibiting thyroid cancer progression, suggesting that ALKBH5 could be a potential target for both the diagnosis and treatment of thyroid cancer." (PMID 40819127, 2025).
systemic lupus erythematosus (8 papers, 2020 to 2025). An autoimmune multi-organ disease typically associated with vasculopathy and autoantibody production. "Meanwhile, ALKBH5 mRNA expression was cardinally cut down in the peripheral blood mononuclear cells of patients with systemic lupus erythematosus (SLE), indicating that ALKBH5 is one of the potential risk factors of SLE." (PMID 40001461, 2025). "Western blot analysis showed elevated expression of the methyltransferases METTL3 and METTL14, and reduced expression of the demethylase ALKBH5 in lupus mice." (PMID 40506739, 2025). "The first available data were focused on the mRNA expression of m6A writers (METTL3, METTL14, and WTAP), erasers (FTO and ALKBH5) and readers (YTHDF2) in peripheral blood mononuclear cells (PBMCs) from lupus affected patients." (PMID 33807762, 2021).
diabetes (7 papers, 2023 to 2026). "The downregulated genes in the RNA‐seq dataset generally had a positive regulatory effect on the disease, which indirectly suggested that ALKBH5 upregulation had a protective effect on myocardial I/R injury in diabetes." (PMID 40548888, 2025). "Further mechanism study showed that ALKBH5 and its mediated m6A can influence osteogenic differentiation, which in turn influences the persistence of diabetic peri-implantitis." (PMID 37519314, 2023). "Our findings present a new mechanism for the suppression of osteoblast development in diabetic peri-implantitis and a new treatment strategy to promote anabolism by inhibiting ALKBH5." (PMID 37519314, 2023). "In summary, our findings provide compelling evidence that in diabetic peri-implantitis, M1 macrophage polarization is increased, ALKBH5 expression is decreased, and m6A modification is elevated, thereby limiting osteoblast development." (PMID 37519314, 2023). "Therefore, ALKBH5 was selected as a starting point for our study in order to investigate its role in the osteogenic differentiation process in diabetic peri-implantitis." (PMID 37519314, 2023).
male infertility (7 papers, 2015 to 2025). The inability of the male to effect fertilization of an ovum after a specified period of unprotected intercourse. "ALKBH5 is an m6A eraser and knocking out Alkbh5 increases the level of total m6A methylation and causes male infertility." (PMID 35368708, 2022). "ALKBH5 deficiency causes male infertility in mice; however, the mechanisms that confer disruption of spermatogenesis are not completely clear." (PMID 35652742, 2022). "In humans, Alkbh5 expression is higher in PA compared with other stages, implying that it affects semen quality and a perturbation in its function increases the risk of male infertility." (PMID 35368708, 2022). "Consistent with ALKBH5 as a dioxygenase that reverses this RNA methylation, depletion of ALKBH5 has been shown to cause accumulation of m6A in mRNA and to be associated with male infertility." (PMID 26294907, 2015). "The inactivation of ALKBH5 led to male infertility through the promotion of the abnormal splicing of certain transcripts in spermatocyte nuclei." (PMID 40001461, 2025). "The ablation of ALKBH5 in mice impeded sperm formation and reduced sperm quantity, ultimately leading to male infertility." (PMID 40001461, 2025). "Overall, we suspect that maintaining physiological level of ALKBH5 is essential for RNA metabolism in germ cells; however, aberrant dysfunction of ALKBH5 may lead to male infertility." (PMID 39239525, 2024). "Knockout (KO) mice lacking the m6A writer (Metll3), eraser (Alkbh5), or reader (Ythdc2) genes have dysfunctions in spermatogenesis that lead to male infertility." (PMID 35652742, 2022).